TNF (tumor necrosis factor)
Diseases named in the same sentence as TNF in open-access papers (continued):
Sharing a sentence is not in itself a finding about the gene and the disease.
Obesity (continued). "Obesity produces greater levels of systemic inflammatory factors, including adipose tissue macrophages, circulating lymphocytes, and pro-inflammatory cytokines (e.g., TNF-α, IL-6, TGF-β1, and C-reactive protein), than is produced in non-obese states." (PMID 27487262, 2016). "GTCs may exert anti-obesity effects through suppression of TNF-α and IL-1β expression, since these inflammatory cytokines are known to upregulate the expression of SREBP-1 and stimulate the maturation of the SREBP-1 protein." (PMID 27689985, 2016). "Neuroinflammation and metabolic disorders such as obesity could act on these mechanisms through an excess of TNFα secretion." (PMID 27012931, 2016). "TNF-α is central to the chronic inflammatory state present in obesity." (PMID 27616737, 2016). "In obesity, macrophages infiltrate adipose tissue and begin to induce proinflammatory cytokines, such as interleukin-1 beta (IL-1β), tumor necrosis factor alpha (TNFα), and interleukin-6 (IL-6), which can interfere with insulin signaling in adipocytes." (PMID 27066503, 2016). "Indeed, pro-inflammatory adipokines, which are upregulated in obesity, such as IL-1α, IL-1β, and TNF-α have been described as potent PAR2 inducers in the vasculature." (PMID 28101054, 2016). "TNFα has been reported to play an important role in adipose tissue inflammation during obesity." (PMID 25685071, 2015). "In obese rats, the neutralization of TNF resulted in increased peripheral glucose uptake induced by insulin, and mice with a TNF gene deletion have significant improvement in their insulin sensitivity in both monogenetic and diet-induced obesity models." (PMID 25918733, 2015). "Furthermore, since the identification of proinflammatory cytokine TNF-α in fat and its relationship to insulin resistance, obesity has been closely related to a low grade chronic inflammatory state." (PMID 25834641, 2015). "In addition, animal experiments have provided evidence that obesity increases TNF-α levels, which results in chronic systemic inflammation." (PMID 26177029, 2015). "Indeed the administration of anti-TNF antibodies in mice resulted in reduced inflammation and the consequent protection against diet-induced obesity and insulin resistance." (PMID 25918733, 2015). "Thus, additionally to ROS, TNFα represents a second important mediator involved in adipose tissue inflammation during obesity." (PMID 25685071, 2015). "The link between obesity inflammation, and abnormal glucose metabolism may in part be related to increased production of pro-inflammatory cytokines such as IL-6 and TNF-α in adipose tissue." (PMID 25994228, 2015). "TNF-α, an adipokine involved in systemic inflammation and a member of a group of cytokines that stimulate the acute phase reaction, has been related to the pathogenesis of both periodontitis and obesity." (PMID 26330934, 2015). "The observation that GM3 treatment of 3T3-L1 adipocytes induces a fourfold increase in IL-6, PAI-1 and TNF-α mRNA suggests that gene expression of proteins involved in obesity induced thrombosis and inflammation may be dependent on its abundance." (PMID 26102277, 2015). "Elevated TNF-α expression in AT from rodent models of obesity was first proposed in 1993." (PMID 26339623, 2015). "Secondly, we only measured hsCRP, complements, and immunoglobulins as inflammatory markers but did not evaluate other markers such as tumor necrosis factor α and IL-6, which were potentially associated with obesity or type 2 diabetes." (PMID 26578821, 2015). "Lowered TNF-α after exercise might have an important role in the obesity reduction and increased immune function." (PMID 26075288, 2015). "Additionally, TNF-α, one of the inflammatory cytokines and a primary modulator of systematic response to infectious diseases, is closely related to obesity." (PMID 26075288, 2015).
Obesity (continued). "In conclusion, our data support a model in which human obesity leads to the elevated expression of IL-6R and IL-6 in the adipose tissue, with increased tissue expression of TNF-α, MCP-1, IP-10 and infiltration by CD11b+/CD163+ macrophages as the underlying features of meta-inflammation." (PMID 26200663, 2015). "Thus, this evidence collectively suggests that obesity and/or diabetes mellitus induces a neuroinflammatory response which upregulates TNFα and other pro-inflammatory cytokines that via multiple pathways leads to an increased risk of neurodegeneration." (PMID 26041981, 2015). "The adipose tissue is considered the prime organ for mediating obesity-induced inflammation by secreting high levels of pro-inflammatory molecules including interleukin (IL)-1, IL-6, and tumor necrosis factor-α (TNF-α) secreted by immune cells residing in the stromal vascular fraction." (PMID 25763111, 2015). "The mechanistic link between obesity, DM, and adipose tissue inflammation was first proposed based on the finding that the level of the proinflammatory adipokine TNFα was increased in adipose tissue of obese rodents and humans and that its blockage led to improvement in insulin sensitivity." (PMID 26578976, 2015). "However, local levels of TNF-α, IL-6 and IL-1 in the placenta are greater in women with obesity compared to healthy controls." (PMID 26569331, 2015). "According to the increased presence of macrophages in the BAL fluid of DIO mice, we could expect that TNF-α plays an important role in the interaction between obesity and asthma." (PMID 25658739, 2015). "In hypertrophic adipose tissue (a frequent characteristic of obesity), NF-κB and HIF-1α are capable of overregulating the expression of genes that encode proinflammatory cytokines, such as IL-6 and TNF-α which, in turn, have direct deleterious effects on the insulin cell signaling pathway." (PMID 25944984, 2015). "Therefore, it is reasonable to postulate that the effects of bilirubin on obesity are a consequence of altered lipid synthesis, reduction of leptin levels, and decreased TNF-α production." (PMID 26017184, 2015). "As a common factor in asthma and obesity, TNF-α might be an important target for treating obesity-related asthma." (PMID 25658739, 2015). "Moreover, the current study showed an increased level of TNF-α which is an important inflammatory cytokine that is overexpressed in adipose and other tissues in cases of IR and obesity." (PMID 25785277, 2015). "A recent study suggested that adipose tissue inflammation in obesity could lead to the repression of beta-Klotho expression by TNF alpha and impaired FGF21 in adipocytes." (PMID 25850006, 2015). "We also showed that restoring normal body weight reduces pulmonary TNF-α levels and then improves typical symptoms of asthma in obesity-related asthma mice, which suggests that restoring normal body weight is an appropriate treatment strategy for obesity-related asthma." (PMID 25658739, 2015). "In accordance with our hypothesis, these results provide further evidence for the presence of a low-grade systemic inflammation in obesity, in which more than the commonly described adipokines IL-1, IL-6 and TNF-α are involved." (PMID 25781614, 2015). "Animal models have shown that a high-fat diet increases systemic and tissue pro-inflammatory cytokines such as bioactive TNF, IL-6, and IL-12, reinforcing the hypothesis that obesity favors a pro-inflammatory microenvironment." (PMID 26074923, 2015). "The pooled results also demonstrated that there was no obvious association of the TNF-alpha (−308 G/A) polymorphism with obesity, or between the IL-1beta (−511 C/T) polymorphism with several clinical and biochemical parameters, in patients with PCOS." (PMID 25634659, 2015). "Also analogous to the periphery is the increased secretion in the CNS of inflammatory cytokines including TNFα as a result of feeding a high fat diet and/or the resultant diet-induced obesity." (PMID 26041981, 2015).
Obesity (continued). "Obesity is considered a state of chronic inflammation as an increase in adipose tissue mass results in greater secretion of inflammatory markers including C-reactive protein, interleukin-6, interleukin-1β, and tumor necrosis factor-α." (PMID 26150767, 2015). "Adiposity, especially abdominal obesity, is the strongest predictor of hsCRP concentrations across different populations, probably resulting from obesity-induced up-regulation of the cytokines IL-6 and TNF-α which contributes to low-grade inflammatory and hsCRP elevation." (PMID 26365713, 2015). "Indeed proinflammatory cytokines secreted from adipocytes are considered as a key step in obesity-induced insulin resistance, as the sole TNF-α neutralization in obese rats is sufficient to improve insulin sensitivity." (PMID 25873766, 2015). "Then, regulation of TNF-α signaling pathway in adipocytes could be one strategy to control undesirable metabolic and immune effects of obesity." (PMID 25789857, 2015). "Low vitamin D levels may also serve as a mechanism contributing to the exacerbation of oxidative stress during obesity, a condition worsened by elevated levels of TNF-α; however, research remains limited." (PMID 26435910, 2015). "We hypothesized that exercise training ameliorates HFD- induced cardiac dysfunction by mitigating obesity and inflammation through upregulation of IL-10 and downregulation of TNF-α." (PMID 25954207, 2015). "More likely, obesity induced chronic production of pro-inflammatory cytokines, in particular TNF-α, may stimulate hepatocytes to overproduce SAA41." (PMID 26563579, 2015). "Taken altogether, we hypothesize that apart from its direct influence on adipose tissue and β cells, TNF-α might contribute to the pathogenesis of obesity and T2D in a Th22-dependent manner." (PMID 24465695, 2014). "Obesity is associated with chronic inflammation, evidenced by increased levels of chemokines/cytokines such as monocyte chemoattractant protein-1 (MCP-1), tumor necrosis factor-α (TNF-α), and increased activation of macrophages in AT." (PMID 25202333, 2014). "Recently, it is reported that the inflammatory cytokines of TNF-α and IL-6 are elevated in sleep apnea and obesity and might play a role in the pathogenesis and pathological sequelae of both disorders." (PMID 24466027, 2014). "Therefore the aim of this study was to evaluate associations between inflammatory markers or cytokines such as IL-6, TNF-α and hsCRP, and both classical and newer obesity parameters and indices in obese normo- and hypertensive subjects." (PMID 24507240, 2014). "Among numerous cytokines, TNF-α was identified as the most important pro-inflammatory mediator in metabolic inflammation, as this cytokine is overexpressed in the adipose tissue of rodent models of obesity." (PMID 24481132, 2014). "In addition to inflammatory lung functions, TNF-α is also involved in a number of severe pathological conditions including Crohn’s disease, rheumatoid arthritis, neuropathic pain, obesity, type 2 diabetes, septic shock, autoimmunity, and cancer." (PMID 25359169, 2014). "Obesity induces changes in serum levels of insulin sensitizing adipokines and also generates a generalized proinflammatory environment by increasing the circulating levels of resistin, interleukin 6 (IL-6) and tumoral necrosis factor alpha (TNF-α)." (PMID 24949022, 2014). "In obesity, chronically elevated TNF-α levels were detected and were also found to be associated with IR, increased plasma glucose and insulin levels IRAS study confirmed that TNF-α is associated with T2D independently of adiposity." (PMID 24736687, 2014). "In the MSG-treated mice model, we found that obesity induced a low-grade chronic inflammatory state accompanied by pro-inflammatory cytokine (TNF-α and IL-6) increments, with adiponectin gene expression reduction and plasma adiponectin elevation following weight loss." (PMID 24979131, 2014).
Obesity (continued). "Using contact cocultured adipocytes/macrophages system and mimicking the inflamed adipose tissue environment in obesity, we first found that the HO-1 induction by hemin significantly reduced levels of inflammatory cytokine (TNF-α and IL-6) release from the cocultures." (PMID 25477711, 2014). "Adipose tissue mass accumulation in the visceral region during obesity has been associated with elevated levels of inflammatory mediators, including serum C-reactive protein (CRP), acute phase proteins and pro-inflammatory cytokines TNF-α and IL-6." (PMID 24979131, 2014). "TNF-α is a pro-inflammatory cytokine that may contribute to the pathogenesis of obesity and insulin resistance." (PMID 24733068, 2014). "TNFα levels are increased in adipose tissue and serum in murine and human obesity." (PMID 24758278, 2014). "Obviously, obesity may represent the primary confounding factor affecting the levels of TNF-α in these works." (PMID 25538852, 2014). "According to previous work, the body weight and epididymal fat of TNFα mutant and WT mice were similar when feeding with a chow diet while both of the mice developed obesity when feeding with a high fat diet for several months, which was consistent with our study." (PMID 24522555, 2014). "Therefore, the overproduction of TNF-α is an important feature of obesity and metabolic inflammation, contributing significantly to insulin resistance." (PMID 24481132, 2014). "The results indicated that obesity promoted IL-6 production, but did not amend spontaneously due to TNFα deficiency." (PMID 24522555, 2014). "In addition, obesity contributes to AD development through the excessive production of inflammatory cytokines by adipose tissue; leptin, tumor necrosis factor (TNFα), and adiponectin, as well as the interleukins ILβ, and IL6 are among them." (PMID 24683436, 2014). "Further, we believe that certain comorbidities, such as diabetes and obesity, could mediate a risk for HBV reactivation among patients treated with anti-TNF-α agents." (PMID 25114684, 2014). "In obesity, fat hypertrophy increases the expression and release of the so-called adipocytokines, such as interleukin (IL) 1β, IL-6, resistin, leptin and tumor necrosis factor alpha (TNF-α), that are necessary for cell differentiation and hematopoiesis, among other functions." (PMID 25184806, 2014). "TNF-α concentrations employed in vitro are often much higher than the plasma concentrations found in human patients with obesity and type 2 diabetes, and therefore it may be difficult to extrapolate from findings obtained in vitro to in vivo." (PMID 24692847, 2014). "In addition, MCP-1 and TNFα mRNA expression was reduced, indicating that obesity-induced inflammation is attenuated in ahKO mice." (PMID 24705496, 2014). "On the other hand, obesity may influence the therapeutic approach and clinical response to systemic treatment in Pso or PsA, especially, the response to anti-TNFα treatment." (PMID 25161652, 2014). "Previous data on obesity, a condition usually linked with insulin-resistance and low chronic inflammation, revealed that circulating levels of sCD163 mirrored particular inflammatory markers such as CRP and TNFα." (PMID 24978196, 2014). "Subgroup analysis taking in consideration the effect of obesity on maternal adipokine levels showed that circulating levels of TNF-α and leptin remained elevated in GDM patients compared to their body mass index (BMI) matched controls, and adiponectin level remained depressed in GDM individuals." (PMID 25202741, 2014). "Furthermore, administration of vaspin suppresses leptin, TNFα, and resistin, reduces food intake, and improves glucose control and insulin sensitivity in obesity." (PMID 24899788, 2014). "Obesity is a low-grade systemic inflammatory condition mediated by cytokines such as TNFα and IL-6." (PMID 25144367, 2014). "Noteworthy, PPARγ is downregulated by AGE and TNFα, overproduced in obesity and type 2 diabetes." (PMID 25361524, 2014).
Obesity (continued). "Insulin and TNF-α, those are augmented in obesity, increased Oip5 mRNA level, suggesting that such obesity-related signals increase the number of preadipocytes partly through Oip5 and provide new adipocytes for fat storage to maintain energy balance in a whole body." (PMID 24516558, 2014). "Obesity-associated VAT macrophages are largely M1 macrophages, or “classically activated macrophages” that secrete large amounts of inflammatory cytokines including TNF-α, IL-6, IL-12, IL-1β, and monocyte chemotactic protein 1 (MCP-1)." (PMID 25157251, 2014). "In obesity, the intra-abdominal adipose tissue growth promotes increased pro-inflammatory cytokines infiltration and activation, such as tumor necrosis factor (TNF-α) and interleukin 6 (IL-6), which denotes the primary causes for chronic inflammation, morbidity and mortality risk." (PMID 24979131, 2014). "Although TNF-α is an inflammatory cytokine produced mainly by monocytes and macrophages, TNF-α produced by adipose tissue may play an important role in obesity-associated insulin resistance and diabetes." (PMID 25105150, 2014). "When we consider areas important in cognition, in db/db mice, a model of metabolic syndrome where obesity arises as a result of leptin receptor insensitivity, IL-1β, TNF-α, and IL-6 mRNA expression levels in the hippocampus are increased when compared to wild type controls." (PMID 25477778, 2014). "Therefore, it was considered that activation of the TNFα system in obesity was a key action to inhibit ongoing weight gain." (PMID 24522555, 2014). "We observed higher serum TNF-α (P = 0.036) levels in cSLE patients with obesity." (PMID 24741576, 2014). "Insulin and TNF-α levels are known to be elevated during obesity in humans and rodents." (PMID 25333972, 2014). "In contrast, obesity causes alteration of the constituent immune cells, in which TH1 cells, B cells, neutrophils, or mast cells induce M1 activation of macrophages by the elevated secretion of TNFα and IFNγ." (PMID 23964268, 2013). "Taken together, all evidence suggests that the interaction between rs651007 and overweight and obesity on serum ALP levels may act through the regulation of TNF system." (PMID 24094242, 2013). "It has been suggested that macrophage accumulation in adipose tissue has a central role in stimulating MMP1 and MMP3 production by preadipocytes, mediated by IL1β and TNFα, supporting the role of macrophages in stimulating tissue remodeling during adipose tissue expansion in obesity." (PMID 23497408, 2013). "Obesity is characterized by an excessive increase in the amount of adipose tissue, which acts as an organ secreting a large variety of proteins, including the proinflammatory cytokines interleukin-6 (IL-6) and TNF-α." (PMID 23533315, 2013). "TNF-α secretion is central in maintaining obesity driven inflammatory loop as it is produced by infiltrated leukocytes from the stromal fraction, and we found that its expression level in adipose tissue was correlated with those of many chemokines in adipose tissue biopsies." (PMID 23824685, 2013). "Moreover, the levels of macrophage M1 phenotype, MCP-1, TNF-α, IL-6, and IL-1β are elevated in obesity and insulin resistance, and these factors play a major pathophysiological role in heart failure." (PMID 24454978, 2013). "Third, because there is limited longitudinal data on changes in these markers among HIV-infected patients with lipohypertrophy or obesity, it is possible that a placebo group would have experienced similar directionality but a greater magnitude of change in TNF-α." (PMID 23516440, 2013). "Our finding of an association between leptin, hsCRP, TNF-α and HOMA with obesity supports the possibility that the increased risk other researchers have observed might be due to a prolonged exposure of arteries to the metabolic milieu." (PMID 24164965, 2013).